OR10AC1 (olfactory receptor family 10 subfamily AC member 1 (gene/pseudogene))
Description:
Odorant receptor.
Synonyms: formerly OR10AC1P
Gene: Protein-coding gene on chromosome 7 (143,509,256 to 143,519,469, reverse strand). Ensembl gene ENSG00000176510.
Subcellular location: Cell membrane
Pathways (Reactome):
Sensory Perception: Expression and translocation of olfactory receptors